OR10C1 (olfactory receptor family 10 subfamily C member 1)
Description:
Odorant receptor.
Synonyms: OR10C2; hs6M1-17; OR10C1P; OR6-31
Tractability: Antibody: UniProt places it where antibodies can reach, with medium confidence; UniProt predicts a signal peptide or a membrane-spanning region; its Gene Ontology location is reachable by antibodies, with medium confidence.
Gene: Protein-coding gene on chromosome 6 (29,439,306 to 29,440,977, forward strand). Ensembl gene ENSG00000206474.
Subcellular location: Cell membrane
Pathways (Reactome):
Sensory Perception: Expression and translocation of olfactory receptors
Gene Ontology:
Molecular function: olfactory receptor activity; G protein-coupled receptor activity
Biological process: detection of chemical stimulus involved in sensory perception of smell; G protein-coupled receptor signaling pathway
Cellular component: plasma membrane; membrane
Genetic constraint (gnomAD): Loss-of-function variants: 0 observed, 0.58 expected, observed/expected ratio (o/e) 0, 90% interval 0 to 1.82. That is too few expected variants to judge how well the gene tolerates losing a copy. Missense variants: 388 observed, 416.16 expected, observed/expected ratio (o/e) 0.93, 90% interval 0.86 to 1.01. Synonymous variants: 183 observed, 185.34 expected, observed/expected ratio (o/e) 0.99, 90% interval 0.88 to 1.12.
Homologues: Orthologues: chimpanzee OR10C1 (97% identical), rabbit OR10C1 (88% identical), mouse Or10c1 (86% identical), rat Or10c1 (85% identical), dog OR10C1 (84% identical). Paralogues in human: OR10A4 (57% identical), OR10A7 (54% identical), OR10A5 (52% identical), OR5V1 (51% identical), OR10A2 (50% identical), OR10A3 (49% identical), OR10P1 (49% identical), OR10A6 (48% identical), OR13C3 (47% identical), OR2D2 (47% identical), OR6A2 (47% identical), OR2K2 (47% identical), and 80 more.